PLK1 (polo like kinase 1)
Diseases named in the same sentence as PLK1 in open-access papers (continued):
Sharing a sentence is not in itself a finding about the gene and the disease.
tumor (continued). "Polo-like kinase 1 (PLK1) plays a pivotal role in cell division and is commonly overexpressed in various types of tumors, making it a model therapeutic gene that has been widely used to evaluate the efficiency of delivery vectors to inhibit tumor growth and improve tumor-bearing mouse survival." (PMID 40214585, 2025). "While PLK1 inhibition in experimental models shows potent antitumoral effects in vitro and in vivo, translation to the clinic has been curbed by modest antitumor activity, tumor relapse, and frequent lack of response." (PMID 39658088, 2025). "The convergence of these results emphasizes the interplay between tumor cell proliferation and immune responses, underscoring the potential for therapeutic strategies that leverage CD4+ T cells to enhance anti-tumor immunity while targeting key cell cycle regulators such as PLK1, CDK1, and CDC20." (PMID 39457373, 2024). "We first compared the expression differences of MAPT, WDR62, PLK1, CDCA8 and TOP2A in normal hepatocyte tissues and HCC tissues by TCGA database, and the results showed that the expression levels of MAPT, WDR62, PLK1, CDCA8 and TOP2A were significantly higher in tumour cells than in normal tissues." (PMID 39072983, 2024). "In addition, PLK-1 expression does not seem to vary significantly with tumor grade or location (left vs. right)." (PMID 39857637, 2024). "In contrast, PLK1 did not display apparent tumor-specific expression pattern." (PMID 38951519, 2024). "The results showed that the C-siPlk1 conjugant was successfully internalized by tumor cells without an axillary agent and suppressed the Plk1 gene both in vitro and in vivo with much higher efficiency than non-viral gene delivery methods such as Lipofectamine 2000." (PMID 38951806, 2024). "AS1411-aptamer-targeted CDEH nanoparticles efficiently inhibit tumor progression as a result of intracellular saporin-specific delivery; folate-targeting CDEH nanoparticles effectively suppress tumor growth on account of joint Cas9 protein and Plk1-targeting sgRNA-selected delivery." (PMID 37110674, 2023). "We found that FOXM1a overexpression significantly decreased the expression of CDC25B, PLK1, and CCNB1 in both CAL 27 and SCC-9 cells, indicating that FOXM1a may inhibit cell proliferation and tumor formation through downregulating the expression of these key genes." (PMID 37759731, 2023). "In addition, PLK1 was mainly highly expressed in classical and proneural subtypes in GBM, which may be related to the presence of tumor stem cells." (PMID 36805592, 2023). "miR-34a directly targets the 3’UTRs of numerous oncogenic mRNAs, including ARAF, CD44, CD117, CDK4, c-Met, cyclin D3, cyclin E2, E2F3, Fra-1, Jagged1, MCM2/5, MET, MYCN, Notch1/2, PIK3R2, PLK1, Smad4, SIRT1/6, and VEGFA, which may contribute to its tumor-suppressive role." (PMID 35961977, 2022). "Presently, although the combination of PLK1 inhibition and immune checkpoint blockade improved overall survival in mouse models – a benefit to patients if recapitulated in the clinic – it failed to induce tumor regressions." (PMID 35871223, 2022). "Rigosertib, an inhibitor of polo-like kinase 1 (PLK1), was identified as a promising drug candidate for the treatment of RDEB-SCC, and was shown to induce G2-M cell cycle arrest and apoptosis in RDEB-SCC cells, as well as inhibiting tumor growth in xenograft studies in vivo." (PMID 35055192, 2022). "Interestingly, we also compared their expression levels between tumor and normal tissues and found that the expressional changes were complex, especially significantly upregulated genes (CDKN2A, MYCN, PLK1, and TERT) and some downregulated signatures (AXL, ID1, and TLR3)." (PMID 35754848, 2022). "In this study, we demonstrated that PLK1 blockade indirectly, rather than directly, elicited DC maturation, which triggered a robust antitumor T cell immune response in an established lung transplantation tumor." (PMID 34522178, 2021).
tumor (continued). "Thus, PLK1-induced phosphorylation of vimentin is a coordinator of metastatic tumorigenesis in LUAD through activation of TGF-β signaling for metastasis and expression of PD-L1 by p-Smad2/3 for tumor survival." (PMID 33963314, 2021). "The therapeutic relevance of the Plk1 inhibitor onvansertib, alone or combined with cisplatin/radiotherapy, was evaluated on the proliferation/migration on HNSCC cell lines, in experimental HNSCC in mice, in a zebrafish metastasis model and on patient-derived 3D tumor sections." (PMID 34646387, 2021). "Our results show that the three tumours responding to volasertib are partially responsive to palbociclib and PDX with primary resistance to palbociclib were also resistant to volasertib, suggesting that cell cycle is the common determinant of response to CDK4/6 and PLK1 inhibitors." (PMID 32792481, 2020). "Notably, the temperature at tumor tissues in this study was controlled at 42 °C or even less, ensuring that the tumor inhibition was attributable to PLK1 knockout rather than a photothermal effect." (PMID 33353099, 2020). "So far, these results imply that PLK1 protein can be used as a shared tumour antigen and PLK1122 is the most effective peptide in generating CD8 T-cells capable of recognising numerous PLK1-expressing tumour cells, resulting in potent therapeutic anti-tumour effects." (PMID 32595211, 2020). "However, intratumoral injections of LP-HAPC-2mol%PEG2000 lipoplexes with PLK1 siRNA also inhibited growth compared with Cont siRNA, indicating that the in vivo anti-tumor effect by PEG-modified siRNA lipoplexes was not correlated with the in vitro one." (PMID 30991703, 2019). "Overexpression of the human Plk1 cDNA, in a conditional inducible knock-in mouse (Plk1-KI), revealed that these mice can tolerate increased levels of Plk1, with no significant higher rates of tumor appearance when compared to control littermates that do not express Plk1." (PMID 30862113, 2019). "However, the cellular effects of Plk1 overexpression in malignant transformation and their implications in tumor development have not been analyzed." (PMID 30069007, 2018). "Additionally, the A10-liposome-scrambled CRISPR/Cas9 group did not reduce tumor volume, suggesting specificity for the PLK1 CRISPR/Cas9 target sequence." (PMID 28030843, 2017). "Interestingly, while knockdown of an essential gene PLK1 induced a remarkable growth inhibition of the subcutaneous tumours of parental MCF7 cells, neither knockdown nor overexpression of COPS5 showed a significant impact on MCF7 tumour growth." (PMID 27375289, 2016). "However, because Plk2 and Plk3 have functions akin to tumor suppression, it is desirable to inhibit Plk1 and not other Plks." (PMID 27874094, 2016). "Loss of FBXW7 is associated with adverse prognostic factors such as tumor grade or non-luminal phenotypes and FBXW7, MCL1 and PLK1 levels may have predictive value in patients treated with paclitaxel." (PMID 27409838, 2016). "This suggests that in tumor cells that do not overexpress PLK1, the low level of PLK1 that is required for cell division could also mediate induction of EMT under certain circumstances, such as in the tumor microenvironment." (PMID 27003818, 2016). "Interestingly, normal cells but not tumor cells can survive from PLK1 depletion, thus PLK1 is a promising target for antitumor therapy." (PMID 23056340, 2012). "Interestingly, not all tumor samples overexpressed PLK1 mRNA, further emphasizing the molecular heterogeneity of this tumor." (PMID 22390279, 2012).
tumor (continued). "Furthermore, in order to determine the importance of PLK-1 in tumor progression, we investigated the effects of PLK-1 knockdown on the biological characteristics of HeLa cells by taking advantage of small interference RNA (siRNA) against PLK-1." (PMID 19775446, 2009). "Treatment with MEKi significantly blunted tumor growth of CDK4i/6i-resistant ALM cells, and the combination of CDK4i/6i + MEKi resulted in the greatest antitumor activity and decrease in cell cycle proteins (pRb, cyclin D, PLK1, FOXM1) relative to what could be achieved by the single-agents alone." (PMID 38066089, 2024). "It is also tempting to speculate, based on the postulated role of both PLK1 and TTK in DNA damage response (see, and references therein) that persistent DNA damage after combined treatment with carboplatin and BAL0891 might contribute to increased tumor cell death." (PMID 39184047, 2024). "Interestingly, targeted ANC@RNP/crEGFR‐PLK1 therapy resulted in significant tumor growth reduction when compared to single gene editing counterparts (ANC@RNP/crEGFR or ANC@RNP/crPLK1), indicating the synergistic role of dual EGFR and PLK1 inhibition in tumor progression." (PMID 38943253, 2024). "Transfection of ectopic PLK1 T210D (a hyper-phosphorylated PLK1 mutant), rather than PLK1 T210A (a hypo-phosphorylated PLK1 mutant), could restore AMPKα2 phosphorylation level in RGCC-deficient and endogenous PLK1 knockout tumor cells." (PMID 38102722, 2023). "Moreover, in RMS, PLK1 inhibition by BI 2536 led to elevated ubiquitination and rapid proteasomal degradation of the PAX3-FOXO1 chimeric oncoprotein in vitro, whereas it reduced PAX3-FOXO1-mediated gene expression and elicited tumor regression in a xenograft mouse model." (PMID 36839989, 2023). "We provided clear evidence that liposomal system co-delivering siPLK-1 and DTX could significantly downregulate expression of PLK-1 and inhibit tumor growth without detectable toxic side effect, compared with siPLK-1-loaded liposomes, DTX-loaded liposomes, and the combinatorial administration." (PMID 35366888, 2022). "Inhibition of PLK1 might increase rather than decrease tumor development in some cases." (PMID 33066048, 2020). "While it is difficult to extrapolate from in vitro tumor cell line suppression to long term clinical benefit in patients, the lack of tumor cell re-growth after combined PLK1 and WEE1 inhibition in our study suggest that this could be an interesting strategy to develop further." (PMID 27558154, 2016). "Moreover, we demonstrated for the first time that iNOP-7 could deliver clinically-relevant amounts of PLK1 siRNA to lung tumors and reduce their proliferation in an orthotopic NSCLC mouse model which closely mimics the tumor microenvironment observed in the clinical setting." (PMID 25557168, 2015). "Moreover, the mRNA of several cell cycle regulatory genes, such as Cdc25b, Cyclin B1, Cyclin A2, Plk1, Cks1, Aurora B, and Topo 2 alpha were decreased in prostates of TRAMP/SPDEF OE mice, a finding consistent with decreased cellular proliferation and decreased tumor sizes." (PMID 25254494, 2014). "Strong immunoreactivity of TFRC, LAMC1, PLK1, and TYMS was observed in tumor tissues, whereas weak or no staining was observed in normal tissues." (PMID 40496862, 2025). "Nevertheless, in the seven-gene model, the remaining four genes—PLK1, TRAF2, SLCO1B3, and ZEB2—though not consistently expressed in tumor epithelial cells, also exhibit either oncogenic or tumor-suppressive functions." (PMID 41187171, 2025). "We did not observe any significant correlation between PLK1 protein levels and clinical or histopathological parameters, including initial ENSAT tumour stage, steroid secretion pattern and Ki67 proliferation index." (PMID 37992487, 2024). "Since PLK1 and TTK had almost no expression, the remaining 5 functional and 2 prognostic MCGs were compared between high/low MC tumor cells." (PMID 39015573, 2024).
tumor (continued). "Both CCNE1 (p < 0.001) and PLK1 (p < 0.001) showed higher expression in tumor tissue than in normal tissue, while the expression of SERPINA1 in both tumor and normal tissue was not significantly different (p = 0.541)." (PMID 36393842, 2022). "Moreover, the strategies that integrate PLK1 blockade and tumor-killers or immunomodulators, which promote the antitumor cytotoxicity and awaken immunity against immunosuppressive TME, might be a promising approach for maximizing the effect of PLK1 blockade in future." (PMID 34522178, 2021). "CYC 140, from Cyclacel Pharmaceuticals, inhibits Plk1 with an IC50 of 3 nM in vitro, and has demonstrated antitumor activity in human tumor xenografts at non-toxic doses." (PMID 34371703, 2021). "The expression of both PLK1 and Ki67 genes was higher in PDX responding with complete response or tumour regression as compared to PDX with no response or partial response to volasertib." (PMID 32792481, 2020). "Unlike most PLK1-PBD peptide inhibitors with poor cellular penetration, peptide 5 is a potential inhibitor that induces mitotic arrest in tumor cells." (PMID 31892137, 2019). "Of note, the co-depletion of MPS1 and PLK1 did not further increase the level of cell death, while the knock-down of MPS1 sensitized tumor cells to sublethal doses of paclitaxel independently of the basal ploidy level." (PMID 26637805, 2016). "Our study revealed that AURKA is a bona fide marker of the severity of the disease whereas PLK1 and MAP9 expression does not correlate with the tumor grade." (PMID 24876664, 2014). "We evaluated the tumor growth patterns of 174 PDX models that were not subjected to any drug treatment and classified them into two groups based on the expression patterns of PLK1 and IGF2BP2." (PMID 40347943, 2025). "The other cell cycle genes analyzed (PLK1, FOXM1, MKI67) were downregulated in romidepsin-treated spheres and PDX-Os but were not changed after romidepsin treatment of the cell line (FOXM1 was increased in the cells) nor tumor implants." (PMID 33035223, 2020). "APA-miRNA–siRNA polyplexes systemically administered to orthotopically inoculated PDAC-bearing mice showed no toxicity and accumulated at the tumor, resulting in an enhanced antitumor effect due to inhibition of MYC oncogene, a common target of both miR-34a and PLK1." (PMID 29295989, 2018). "However, the higher expression of PLK1 in HCC was found in well differentiated tumor cells and tumor without capsule invasion, but not in moderate and poor differentiated cells and tumor with capsule invasion." (PMID 25019081, 2014). "However, we only observed the physical interaction of SHCBP1 with RACGAP1 and MKLP1, but not with PLK1 in asynchronous tumour cells, suggesting that SHCBP1 may only interact with PLK1 in the mitotic phase." (PMID 38365687, 2024). "Systemic in vivo delivery of miR-34a and PLK1-siRNA by our APA nanocarrier, which facilitated accumulation preferably at the tumor site and internalization into the tumor cells, efficiently inhibited tumor growth in an orthotopic mouse model, with no systemic side effects nor immunotoxicity." (PMID 29295989, 2018). "Thus, UBC and PLK-1 on one hand and negative control siRNA1 and siRNA2 on the other hand defined a range among which candidate genes were ranked according to their impact on CTL-mediated tumor lysis." (PMID 25691366, 2015).
infection (21 papers, 2008 to 2026). The state of being infected such as from the introduction of a foreign agent such as serum, vaccine, antigenic substance or organism. "The prevalence of up-regulated kinase genes highlights a prominent activation of intracellular signaling processes in late-stage infection (Aurka, Aurkb, Cdk1, Tk1, Plk1, Pbk, and Melk) in this article." (PMID 38107402, 2023). "On the other hand, cohesion of sister chromatids is a dynamic process regulated by genes such as Cdca5, Cdca8(Borealin), Plk1, Sgo1, and Sgo2a, which were up-regulated late in infection." (PMID 38107402, 2023). "More importantly, the infection of HIV-1 enhances PLK1 SUMOylation to stabilize PLK1 and promotes its nuclear localization, which inhibits viral cytopathic effects-induced cell death." (PMID 37112965, 2023). "In this study, we identified that polo-like kinase 1 (PLK1) is induced by KSHV de novo infection as well as lytic switch from KSHV latency." (PMID 34297745, 2021). "Especially, they found that the dynamic pattern of cell cycle genes such as CDK1, AURKA, and PLK1 are upregulated in early infection (4 hpi), and this upregulation tends to peak at 24 hpi and then precipitously decrease." (PMID 33060827, 2020). "We identified 11 genes that were significantly altered after infection with both viruses, and among these genes, 6 were up-regulated after infection (Chl1, Nlrp12, Plk1, Cyfip2, Adamts3, and Pdzk1)." (PMID 30713529, 2018). "Infection of cells with lentivirus expressing miRNA-resistant Plk1 effectively generated stable Plk1 expressing cells." (PMID 30135525, 2018). "Plasmid expressing PLK1-myc fusion protein was transfected into HeLa cells at 3 days after infection with LV-shRNA-lnc-RI." (PMID 27160062, 2016). "Forty eight hours post infection, we found that over-expression of wild-type (WT) Plk1 increased the number of HeLa cells by 23±5.6% (n = 3, p = 0.02), compared to the EGFP control." (PMID 19707596, 2009). "Polo-Like Kinase-1 (PLK1) showed downregulation at 12 hr post infection in both the cell types." (PMID 24278205, 2013). "A role for PLK1 in infection by other viruses has been reported recently." (PMID 19629176, 2009). "Additionally, as the duration of infection increases, aging-related genes Plk1, Cenpa, Bub1b, H2afx, and Cdkn2d were activated, suggesting that infection may initiate cellular senescence." (PMID 41827050, 2026). "Of note, in G1/S-arrested cells, vDNA remained Golgi-associated after infection at least until 72h p.i., suggesting that it served as efficient ‘waiting room’ for HPV until cell cycle progression into mitosis and, thus, CDK1- and PLK1-mediated phosphorylations of L2 would occur." (PMID 36683055, 2023). "Further study found that PLK1 is elevated by HIV-1 Nef upon HIV-1 reactivation, as well as de novo infection." (PMID 37112965, 2023). "In PT45 cells, AdΔ19K, but not Ad5, significantly induced Plk1 phosphorylation 48h post-infection." (PMID 26872382, 2016).
hematologic malignancies (7 papers, 2010 to 2025). "Clinical trials of Plk1 in combination with other chemotherapeutic agents have also shown good tolerability and significant clinical activity in hematological malignancies." (PMID 40166466, 2025). "PLK1 inhibitors, such as rigosertib and volasertib, in combination with the Aurora A inhibitor alisertib, have shown beneficial effects in treating hematologic malignancies and solid tumors." (PMID 41154590, 2025). "PLK1 has central roles in the transition from G2 to M-phase and is considered a proto-oncogene because it activates the PI3K/Akt/mTOR signaling pathway in ALL and other hematological malignancies." (PMID 35445848, 2022).
adenocarcinoma (6 papers, 2020 to 2025). A common cancer characterized by the presence of malignant glandular cells. "To investigate the clinical significance of PLK1 expression in NSCLC, we firstly analyzed the expression profiles of PLK1 in 483 adenocarcinoma (LUAD) samples and 347 normal lung samples from The Gene Expression Profiling Interactive Analysis data." (PMID 40355412, 2025). "In clinical analysis of adenocarcinoma patients with stage 1 (middle), patients with high PLK1/VIM/CD274 had shorter OS times than those with low PLK1/VIM/CD274 (n = 346, HR = 2.527, log rank P = 0.0246)." (PMID 33963314, 2021). "Heatmap analysis revealed upregulated VIM and PLK1 mRNA expression in TGF-β-treated adenocarcinoma when the mesenchymal markers CDH2, SNAI1, and SNAI2 were high and either CDH1 or OCLN (epithelial markers) was low in majority of LUAD cells analysed." (PMID 33963314, 2021). "In a clinical analysis of 360 adenocarcinoma patients with stage 1, those with high levels of PLK1/VIM had shorter OS than those with low PLK1/VIM levels (n = 360, HR = 2.090, log rank P = 0.019)." (PMID 33963314, 2021).